GSTM1 (glutathione S-transferase mu 1)
Diseases named in the same sentence as GSTM1 in open-access papers (continued):
Sharing a sentence is not in itself a finding about the gene and the disease.
breast carcinoma (continued). "Moreover, the results of recent studies suggest that for alcohol drinkers interactions with GSTM1 and GSTT1 deletion polymorphisms may play an important role in individual susceptibility to breast cancer." (PMID 12556960, 2003). "We suppose that prolonged exposure to estrogen levels combined with an inefficient detoxification due to GSTM1 and GSTT1 null genotype are related to breast cancer development at later ages." (PMID 33513690, 2021). "Upon cholesterol treatment, there is a significant increase in the expression of metabolic target genes of ERRα, including IDH3A, VEGF, PDK4, SOD2, GSTM1, and SPP1, in breast cancer cells." (PMID 32717915, 2020). "Several studies reported the frequency of the GSTM1 and GSTT1 null genotype in breast cancer patients." (PMID 32856852, 2020). "The frequencies of the GSTM1 and GSTT1 null genotypes in 198 breast cancer patients were 65.70% and 33.30%, respectively." (PMID 32856852, 2020). "This study performed GSTM1 and GSTT1 genotyping in 136 breast cancer cases and sex- and age-matched 136 clinically healthy controls by multiplex PCR." (PMID 30803216, 2019). "Overall anemia (grade 1–2) high risk genetic factors belonged to all three functional groups – DNA repair (ERCC1, p.Asn118=), metabolism (GSTT1 and GSTM1 present) and transport (ABCC2, p.Val417Ile), with addition of breast cancer triple negativity." (PMID 29507678, 2018). "We investigated whether GSTT1 (“null” allele), GSTM1 (“null”allele), GSTP1 (A313G), RFC1 (G80A), MTHFR (C677T), TS (2R/3R) polymorphisms were associated with toxicity and survival in patients with early breast cancer (EBC) treated with adjuvant chemotherapy (CT)." (PMID 28747156, 2017). "Ambrosone and colleagues evaluated the role of GSTM1- and GSTT1-null genotypes on disease-free and overall survival among 251 women who received treatment for incident, primary breast cancer." (PMID 20459744, 2010). "It is thus significant that cholesterol binding to ERRα and cholesterol-mediated increase in ERRα-PGC-1α interaction result in increased expression of ERRα itself and its metabolic target genes including IDH3A, VEGF, SOD2, GSTM1, PDK4, SPP1 in breast cancer cells." (PMID 32717915, 2020). "In contrast, some researchers reported that GSTM1 and GSTT1 polymorphisms did not increase a substantial risk of breast cancer and prostate cancer." (PMID 21629772, 2011). "In our previous data, the effect of GSTT1 and GSTM1 gene deletions on survival after treatment of breast carcinoma was not evident in the entire population." (PMID 18423013, 2008). "In our data, the effect of GSTT1 and GSTM1 gene deletions on survival after the treatment of breast carcinoma was not evident in the entire population." (PMID 14562023, 2003). "None of the GSTM1 genotypes, either alone or in combination with GSTT1 genotypes, was associated with breast carcinoma in the different subgroups." (PMID 14562023, 2003). "Interestingly, genetic variants within the GSTM gene cluster—particularly in GSTM3—have been associated with cancer susceptibility in breast cancer, where certain GSTM3 SNPs conferred increased risk only in individuals lacking GSTM1 expression." (PMID 40868127, 2025). "This study suggests that variants of GSTM1 and GSTT1 may not be risk factors for breast cancer development among Filipinos." (PMID 30803216, 2019). "Although this study shows lack of association of the GSTM1 and GSTT1 null genotypes with breast cancer, it should be noted that an interplay of genetic predisposition with environmental and lifestyle factors plays a role in increased susceptibility to breast cancer." (PMID 30803216, 2019). "Indeed, our results could not find the relation of GSTM1 and GSTT1 gene polymorphisms and the overall survival among patients with breast cancer treated with chemotherapy." (PMID 32856852, 2020).
breast carcinoma (continued). "Smaller studies have reported that smoking did not modify associations between GSTT1, GSTM1, or GSTP1 polymorphisms and breast cancer, whereas former smokers with GSTT1 null were found to have an increased risk of breast cancer compared with never smokers with GSTT1 present." (PMID 19440493, 2009).
bladder cancer (45 papers, 1999 to 2025). "These loci included 14 previously reported bladder cancer-associated genes (eg, GSTM1 and NAT2) and 3 novel loci near MSX2, RAPGEF5, and MIPOL1 genes." (PMID 39898788, 2025). "The GSTM1 genotype, which is a risk factor for bladder cancer, was therefore determined indirectly via a proxy marker in some GWAS for bladder cancer, for example." (PMID 40630467, 2025). "Available evidence indicates that homozygous for the GSTM1-null genotype carry a higher risk for bladder cancer, particularly if exposed to certain toxicants, like asbestos, rubber, and chlorinated solvents." (PMID 39898788, 2025). "Liver enzymes, notably metabolic detoxification enzymes like UDP-glucuronosyltransferases (UGTs) and glutathione-S-transferase M1 (GSTM1), exhibit gender-specific differences, affecting carcinogen detoxification and thus bladder cancer risk." (PMID 38283839, 2023). "Previous studies suggested that the GSTM1 null polymorphism has been linked with an increased risk of bladder cancer, especially among smokers." (PMID 34452561, 2021). "The current study shows that tobacco smokers with the NAT2 low acetylator phenotype and GSTM1 null genotype have the highest risk of bladder cancer in the Mongolian population." (PMID 34452561, 2021). "We have shown, however, that GSTM1 null genotype in combination with tobacco smoking (OR=5; 95% CI=1.55-16.16) increase significantly the risk of bladder cancer (p=0.007)." (PMID 34452561, 2021). "Smokers with GSTM1 null genotype were at 5-fold higher risk of bladder cancer (OR=5.0; 95% CI=1.55-16.16), (p=0.007) while NAT2 low acetylator phenotype increased bladder cancer risk by 20-fold (OR=20.5; 95% CI=2.33-80.86), (p=0.006)." (PMID 34452561, 2021). "Smokers with GSTM1 null genotype were at five-fold higher risk of developing bladder cancer (OR=5.0; 95% CI=1.55-16.16) while the risk was even higher with twenty-fold with NAT2 low acetylator phenotype (OR=20.5; 95% CI=2.33-80.86)." (PMID 34452561, 2021). "It has been reported by several investigations that the GSTM1 null genotype increases the risk of bladder cancer, especially among smokers." (PMID 34452561, 2021). "In our investigation we examined the frequency of GSTP1 and GSTM1 variants in a cohort of 93 bladder cancer patient from Saudi Arabia." (PMID 31646988, 2019). "Previous studies on patients from different ethnic origins revealed that individuals with the null GSTM1 were at high risk of developing bladder cancer." (PMID 31646988, 2019). "We also attempted to evaluate the clinical significance of HER2 status in cases confirmed to have GSTM1/ GSTP1 variants with bladder cancer prognosis." (PMID 31646988, 2019). "The present study revealed that GSTM1 null genotype is significantly associated with poor overall survival in urinary bladder cancer patients." (PMID 31646988, 2019). "Our results indicated a significant association between the null GSTM1 genotype and poor overall survival among bladder cancer patients." (PMID 31646988, 2019). "We also evaluated the association between GSTP1 and GSTM1 gene polymorphisms with a set of clinical and pathological parameters as well as the prognostic value of both genes polymorphisms in bladder cancer patients." (PMID 31646988, 2019). "They reported a strong correlation between single gene deletion ‘GSTM1 or GSTT1’ or double deletions of GSTM1/GSTT1 with a higher risk of bladder cancer, especially among Caucasians and Asians." (PMID 30630456, 2019). "Here, we describe the evolutionary forces that shape the variation in the GSTM1 gene, which has been shown to be an important metabolism gene and associated with bladder cancer, autoimmune disorders and response to different drugs." (PMID 30061374, 2018). "The common deletion of the glutathione S-transferase Mu 1 (GSTM1) gene in humans has been shown to be involved in xenobiotic metabolism and associated with bladder cancer." (PMID 29695243, 2018).
bladder cancer (continued). "Stratified analyses of population-based association study showed a significant association of increased bladder cancer risk with GSTM1 null and GSTM1/GSTT1 double-null in HB studies and PB studies." (PMID 27911277, 2017). "Stratified analyses of population-based association showed a significant association of elevated bladder cancer risk with GSTM1 deletion in hospital-based (HB) studies (OR=1." (PMID 27911277, 2017). "GSTM1 genetic polymorphisms have been implicated in many diseases including atherosclerosis, and bladder cancer." (PMID 28596482, 2017). "Stratified analyses of population-based association showed association of elevated bladder cancer risk with GSTM1/ GSTT1 double-null in HB studies (OR=1.73, 95%CI=1.45-2.23) and PB studies (OR=2.28, 95%CI=1.22-4.25)." (PMID 27911277, 2017). "This meta-analysis demonstrates that the GSTM1-null, GSTT1-null, and GSTM1/GSTT1 double-null genotypes are associated with increased bladder cancer risk." (PMID 27911277, 2017). "Regarding the different ethnicities, our results suggest that the GSTM1 null genotype is associated with the elevated risk of bladder cancer in Caucasians and Asians." (PMID 27911277, 2017). "The GSTM1/GSTT1 double-null genotype was associated with increased risk of bladder cancer in Caucasians, Asians, and Africans." (PMID 27911277, 2017). "Stratified analyses of population-based associations indicated increased bladder cancer risk associated with GSTM1-null and GSTM1/GSTT1 double-null genotypes in hospital-based and population-based studies." (PMID 27911277, 2017). "The pooled meta-analysis showed that individuals with GSTM1/ GSTT1 double-null genotype were at a higher risk to develop bladder cancer than individuals with GSTM1 or GSTT1 present." (PMID 27911277, 2017). "The pooled meta-analysis showed that the GSTM1 null genotype was associated with increased risk of bladder cancer." (PMID 27911277, 2017). "The GSTM1 null genotype was also associated with elevated risk of bladder cancer stratified by smoking status (OR 1.37, 95%CI: 1.19-1.59 for smokers and OR 1.26, 95%CI: 1.08-1.48 for non-smokers, respectively)." (PMID 27911277, 2017). "The GSTM1/ GSTT1 double-null genotype was associated with the elevated risk of bladder cancer in Caucasians (OR=1.23, 95%CI=1.08-1.40), Asians (OR=2.05, 95%CI=1.53-2.74) and Africans (OR=6.29, 95%CI=1.62-24.47)." (PMID 27911277, 2017). "GSTM1 null, GSTT1 null and GSTM1/GSTT1 double-null genotypes were associated with increased risk of bladder cancer (OR: 1.36 95% CI: 1.25-1.47, P<0.01; OR: 1.13 95% CI: 1.02-1.25, P<0.01; OR: 1.84 95% CI: 1.50-2.26, P<0.01)." (PMID 27911277, 2017). "The GSTM1 null genotype was associated with the elevated risk of bladder cancer in Caucasians (OR=1.34, 95%CI=1.21-1.48) and Asians (OR=1.50, 95%CI=1.31-1.71)." (PMID 27911277, 2017). "Some reports have summarized that smoking increases the risk of bladder cancer in people with GSTM1-null genotype." (PMID 27404495, 2016). "GSTM1 is an important anti-oxidant enzyme in cells, and loss of the GSTM1 gene is known to be correlated with human bladder cancer." (PMID 27404495, 2016). "In fact, the GSTM1 gene activity in humans is mainly inhibited by gene loss, and the GSTM1-null status is associated with a modestly increased risk of bladder cancer." (PMID 27404495, 2016). "The homozygous deletion resulting in functional loss of the GSTM1 enzyme has been implicated in the genesis of several cancers, including cervical neoplasia, colorectal cancer and bladder cancer." (PMID 24194954, 2013). "An association signal was detected (OR = 0.66, p = 1.74 × 10-3) using this method adjusting for age, gender, region and tobacco use, replicating the known association between GSTM1 and bladder cancer." (PMID 22817656, 2012). "CNV callings provided by TaqMan and MLPA were highly concordant and replicated the association between GSTM1 and bladder cancer." (PMID 22817656, 2012).
bladder cancer (continued). "The mechanism underlying associations between bladder cancer and the GSTM1-null genotype is not yet well understood." (PMID 20675267, 2010). "He presented the results of a previously published study on the association between N-acetyl transferases 2 (NAT2) and gluthatione S-transferases-M1 (GSTM1) polymorphisms with bladder cancer risk." (PMID 22275976, 2008). "Specifically, the GSTM1 null genotype increases the overall risk of bladder cancer; while the NAT2 slow acetylator genotype appears to increase risk particularly among cigarette smokers." (PMID 17319747, 2007). "We did observe a statistically significant interaction between the GSTM1 null genotype, cigarette smoking, and bladder cancer risk in males (p for interaction = 0.02)." (PMID 17026750, 2006). "The GSTM1 null polymorphism has been consistently associated with an increased risk of bladder cancer in pooled and meta-analyses." (PMID 17026750, 2006). "Our analyses showed a consistent association between GSTM1 and bladder cancer risk." (PMID 39898788, 2025). "Our results show that the GSTM1 null genotype is associated with increased bladder cancer risk." (PMID 27911277, 2017). "In addition, our results indicate that the GSTM1/GSTT1 double-null genotype is associated with elevated risk of bladder cancer in Caucasians, Asians, and Africans." (PMID 27911277, 2017). "However, different from mice, the human GSTM1 gene has been reported to be deleted in approximately 50% population, and the GSTM1-null genotype is reported to be more susceptible to bladder cancer." (PMID 27404495, 2016). "For example, a case–control study conducted in the US showed that the association between cruciferous vegetable intake and bladder cancer risk might be modified by the GSTM1 genotype, and the protective effect of cruciferous vegetables was observed only in subjects carrying the NAT2-slow genotype." (PMID 37828430, 2023). "Furthermore, loss of the GSTM1 gene is known to be correlated with human bladder cancer." (PMID 33802702, 2021). "GSTM1 (glutathione S‐transferase M1) is a member of the family of cytosolic GSTs, and the null genotype of GSTM1 has been proven to be associated with risk of colorectal cancer, renal cell carcinoma, oesophageal cancer, nasopharyngeal cancer and bladder cancer." (PMID 33259129, 2021). "Due to the established role of GSTM1 in detoxification and the high frequency of homozygous deletions in the population, GSTM1 has been extensively investigated in association with many chronic diseases, in particular, with asthma and different types of cancers, including bladder cancer." (PMID 22817656, 2012). "Indeed, applying the callings provided by TaqMan and MLPA in this sample, we obtained a significant association (p = 3.40 × 10-4, OR = 0.74 [0.62-0.87] and p = 1.15 × 10-4, OR = 0.72 [0.61-0.85], respectively) between the trend on the number of copies at GSTM1 and bladder cancer risk." (PMID 22817656, 2012). "For all 3 proteins (GSTM1, GSTM4, and KLC1), there was strong evidence of colocalization (ie, PH4 ≥ 0.8), indicating that the protein and bladder cancer share a joint causal variant." (PMID 39898788, 2025). "Polymorphisms: GSTO2*N142D (A424G; rs156697) and other GSTs (GSTP1, GSTM1, GSTT1, GSTZ1)Main findings:- positive association between GSTO2*N142D variant and bladder cancer risk independently of arsenic exposure." (PMID 40724836, 2025). "Additional clinical data is required to verify the relationship between GSTM1 and gender differences in bladder cancer." (PMID 38283839, 2023). "In conclusion, our current study shows that in the Mongolian population, the risk of developing bladder cancer was the highest for tobacco smokers with the NAT2 low acetylator phenotype and GSTM1 null genotype." (PMID 34452561, 2021). "Several studies have demonstrated the relationship between genetic polymorphisms of GSTM1, NAT2 and bladder cancer risk." (PMID 34452561, 2021).
bladder cancer (continued). "Smoking also increases the odds ratio of bladder cancer in individuals with the GSTM1-null genotype." (PMID 33802702, 2021). "We evaluated the effect of GSTM1 genotype and NAT2 phenotypes on the risk of bladder cancer after adjustment by sex and age." (PMID 34452561, 2021). "PCR-RFLP assay was used to determine the presence of GSTM1 and NAT2 polymorphisms in bladder cancer patients and controls." (PMID 34452561, 2021). "Our current study investigates combined effect of tobacco smoking and GSTM1, NAT2 genotypes on the risk of developing bladder cancer in Mongolian population." (PMID 34452561, 2021). "The association between GSTM1, NAT2 phenotypes and the risk of bladder cancer was significant in smokers (p=0.007), (p=0.006) respectively." (PMID 34452561, 2021). "Polymerase chain reaction-based and Sanger gene sequencing-base assays were undertaken to assess the contribution of genetic polymorphism in GSTM1 and GSTP1 to the susceptibility of bladder cancer." (PMID 31646988, 2019). "Our data revealed that a total of 44 bladder cancer patients out of 93 (47.31%) had a GSTM1-deleted genotype (−/−)." (PMID 31646988, 2019). "In a meta-analysis that included 63 studies, they studied the possible association between GSTM1 or GSTT1 polymorphism and bladder cancer susceptibility." (PMID 30630456, 2019). "In the same context and for the first time we investigated the relationship between different GSTP1/GSTM1 variants and Human Epidermal growth factor Receptor 2 (HER2) gene/ protein status in bladder cancer patients." (PMID 31646988, 2019). "In the present study, we aim to investigate the prognostic value of GSTM1 and GSTP1 genetic polymorphisms in patients with bladder cancer and evaluate their association with patients’ clinicopathological parameters." (PMID 31646988, 2019). "To quantify the strength of the association between GSTM1/GSTT1 polymorphisms and bladder cancer risk, we performed a meta-analysis of 63 studies." (PMID 27911277, 2017). "Previous meta-analyses have indicated an association of GSTM1 and GSTT1 deletion polymorphisms with increased bladder cancer risk; however, the results have been inconsistent." (PMID 27911277, 2017). "Here, we performed a meta-analysis to investigate the association between GSTM1/GSTT1 deletion polymorphisms and bladder cancer susceptibility." (PMID 27911277, 2017). "Here, we performed an updated meta-analysis to investigate the association between GSTM1/GSTT1 deletion polymorphisms and bladder cancer susceptibility." (PMID 27911277, 2017). "GSTM1, an antioxidant enzyme related to bladder cancer development, is down-regulated in protein and mRNA levels by BBN that are partially mediated by DNA methylation." (PMID 29016672, 2017). "We searched for all studies investigating the association between GSTM1 or GSTT1 polymorphism and bladder cancer susceptibility in Pubmed, Web of Knowledge, and the Cochrane Central Search Library." (PMID 27911277, 2017). "In summary, our meta-analysis study indicates that GSTM1 null, GSTT1 null, and GSTM1/GSTT1 double-null genotypes are associated with increased bladder cancer risk." (PMID 27911277, 2017). "Previous studies have indicated association between GSTM1 and GSTT1 gene polymorphisms and bladder cancer susceptibility, but the results have been inconclusive." (PMID 27911277, 2017). "Among 7 human bladder cancer cell lines, GSTM1 gene is really null in 6 cell lines except one, T24 cells." (PMID 27404495, 2016). "Previous studies have investigated the relationship between GSTA1, GSTM1, GSTP1, and GSTT1 polymorphisms and bladder cancer (BCa) susceptibility, respectively, but the results remain inconsistent." (PMID 27631264, 2016). "In our previous study, we found that GSTM1 mRNA and protein levels were increased by 5-aza-dC treatment in human bladder cancer 5637 cells." (PMID 27404495, 2016).